INS (insulin)
Diseases named in the same sentence as INS in open-access papers (continued):
Sharing a sentence is not in itself a finding about the gene and the disease.
type 2 diabetes (continued). "The loss of insulin-producing pancreatic β cells will reach approximately either 70%–100% in type 1 diabetes (T1D), due to islet β cell directed autoimmunity, or up to 65% in type 2 diabetes (T2D), depending upon miscellaneous factors, such as glucotoxicity, amyloid deposits and inflammation." (PMID 37180045, 2023). "Type 2 diabetes (T2D) is characterized by hyperglycemia caused by insufficient insulin release from pancreatic islets, often in combination with insulin resistance." (PMID 38086799, 2023). "Variants associated with the highest values of age- and sex-specific insulin showed associations with above-median values of log-insulin but not with values below the median, and were often located in genes that had been found to be related to type 2 diabetes in previous studies." (PMID 37420130, 2023). "Acylcarnitines are derived from mitochondrial acyl-coenzyme A (CoA) metabolism, and the accumulation of acylcarnitines can interfere with insulin signaling in type II diabetes and thus may be associated with higher risks of impaired glucose tolerance and type II diabetes in IUGR." (PMID 37990266, 2023). "Given that metformin, SGLT2 Is, GLP‐1 RAs and alpha‐glucosidase inhibitors may be beneficial for weight loss, while sulfonylureas, thiazolidinediones and insulin may be associated with weight gain, weight loss observed in type 2 diabetes patients nowadays are more likely to result from medication." (PMID 36756713, 2023). "Pregnant women with type 1 and type 2 diabetes experience regular strain and burden associated with daily self-management, involving frequent self-monitoring of blood glucose, accurate titration of insulin doses to blood glucose measures and carbohydrate intake, and close health monitoring." (PMID 37131168, 2023). "Type 2 diabetes mellitus (T2DM), mainly caused by abnormal insulin signaling transduction, accounting for approximately 90% of cases." (PMID 37764863, 2023). "Similarly, type 2 diabetes may increase PCa risk by influencing insulin and insulin-like growth factor pathways, potentially enhancing the carcinogenic impact of certain workplace exposures." (PMID 37763224, 2023). "Also, the kidneys play an important role in the clearance of insulin and impaired kidney function could have influenced insulin levels in addition to underlying metabolic disturbances related to type 2 diabetes." (PMID 37716952, 2023). "Moreover, this CpG is located in the transcription start site of the WNT5B gene, known to be associated with adipogenesis, insulin secretion, and type 2 diabetes, which could represent a potential biological mechanism via DNA methylation." (PMID 35236238, 2022). "Thus, hepatocyte‐directed IL‐1 inhibition could be an adjunctive strategy to weight loss in obese patients to improve hepatic insulin resistance, mitochondrial dysfunction, and ultimately the risk to develop overt type 2 diabetes." (PMID 36101976, 2022). "Since glucose-induced insulin secretion is impaired by hydroxynonenal, the resultant hyperglycemia conceivably causes an increase of oxidative stress with the subsequent acceleration of lipid peroxidation which facilitates generation of hydroxynonenal to worsen type 2 diabetes." (PMID 36819480, 2022). "Specifically, type 2 diabetes (T2D) is a polygenic disease that is caused by a complex interplay between genetic, epigenetic, and environmental factors, with most of the associated genomic regions affecting the regulation of β-cell function focusing on the secretion and resistance of insulin." (PMID 35627158, 2022). "In particular, we have demonstrated that adult onset diabetes patients who are 3-Screen positive present a characteristic clinical phenotype associated with poor β-cell function and should be monitored more closely particularly with respect to their requirement for insulin." (PMID 34533636, 2022).
type 2 diabetes (continued). "In patients with type 2 diabetes at high risk of hypoglycaemia, risk of inpatient/emergency department‐related hypoglycaemia was significantly lower during 12 months after switching to insulin glargine 300 units/mL, compared with switching to insulin glargine 100 units/mL or insulin detemir." (PMID 34807513, 2022). "Type 2 diabetes mellitus (T2DM) is a common metabolic-associated disease, which is characterized by chronic hyperglycemia resulting from impaired insulin secretion, insulin resistance or a combination of both." (PMID 36591472, 2022). "Randomized controlled trials show that testosterone treatment improves insulin sensitivity in men at risk for type 2 diabetes mellitus (T2DM); prevents the development of T2DM in men at risk for T2DM; and, improves glycemic control in men with T2DM." (PMID 36152143, 2022). "However, it is not known whether the increase in Sct relative expression causes continuous increased insulin release and consequently type 2 diabetes development." (PMID 35203869, 2022). "In addition, our previous reports demonstrated that ethanol-fed mice were closely associated with the alteration of glucose and insulin metabolism, which is strongly related to the development of type 2 diabetes through pancreatic β-cell dysfunction and apoptosis." (PMID 35819975, 2022). "Type 2 diabetes mellitus (T2DM) is a highly prevalent metabolic disorder characterized by elevated blood glucose levels, primarily caused by insulin secretion disturbance, insulin resistance, or both." (PMID 35711668, 2022). "Moreover, researchers have reported that lower levels of high molecular weight adiponectin in postmenopausal women were significantly associated with a higher BMI, type 2 diabetes, hypertension, glucose, and insulin levels, and lower HDL-C levels (P < 0.01 for all)." (PMID 35549892, 2022). "Moreover, high MUFA and PUFA diets may improve insulin sensitivity, reduce type 2 diabetes risk and improve cardiovascular outcomes." (PMID 35413879, 2022). "Type 2 diabetes mellitus (T2DM) is a chronic metabolic disease caused principally by insulin dysfunction." (PMID 35626992, 2022). "Emerging evidence in recent years has linked and type 2 diabetes mellitus (T2DM) and its insulin dysregulation to worsen PD outcomes." (PMID 35886849, 2022). "Type 2 diabetes mellitus (T2DM) is a metabolic disease characterized by high blood sugar caused by impaired insulin activity." (PMID 36465647, 2022). "Although obesity is associated with an increase in beta cell mass, by the time type 2 diabetes develops, there has been a 65% reduction in beta cell mass due to apoptosis associated with increased levels of amylin that is secreted in equimolar amounts to insulin." (PMID 35163806, 2022). "In addition, thyroid hormones may cause pathological conditions that in turn act as risk factors for type 2 diabetes, such as an increased body mass index and impaired insulin secretion." (PMID 35137143, 2022). "The development of type 2 diabetes mellitus (T2DM) is a result of insulin resistance (IR) in organisms, which is associated with an inability of insulin to stimulate glucose uptake by target cells and to reduce the blood glucose concentration." (PMID 36558167, 2022). "We note that disrupted insulin and cerebral glucose metabolism are seen even in medication-naïve first-episode schizophrenia, suggesting that people with schizophrenia are at risk for Type 2 diabetes and cardiovascular disease, resulting in a shortened life span." (PMID 36483840, 2022). "Type 2 diabetes mellitus (T2DM) is linked with insulin's inability to respond to a glucose increase." (PMID 36120233, 2022). "Yet, a β-cell specific THR agonist, similar to the one designed for liver to treat hyperlipidemia could be developed to induce proliferation of β-cells as a potential therapeutic for both type 1 and type 2 diabetes where there is a deficiency in functional insulin producing cells." (PMID 36455788, 2022).
type 2 diabetes (continued). "Type 2 diabetes mellitus (T2DM) is a chronic metabolic disease characterized by disordered sugar, fat, and protein metabolism caused by insufficient islet secretion of insulin or insulin resistance (IR)." (PMID 35911164, 2022). "Differences in sensitivity to metabolic hormones and adipokines, such as leptin and insulin, may underlie some of the sex differences in the prevalence of type 2 diabetes and obesity, and interestingly, these hormones and adipokines are often altered by the nutritional environment of early life." (PMID 36439251, 2022). "Type 2 diabetes (T2D) is a complex and multifactorial disease, which is mainly caused by an insufficient pancreatic β cell response to insulin resistance." (PMID 35614067, 2022). "In the two decades since the fetal insulin hypothesis was first proposed, advances in genetic research have shed light on what contributes to fetal insulin-mediated growth and its implications for long-term risk of type 2 diabetes." (PMID 33569631, 2021). "Thus, the change in retinal arterial stiffness by insulin treatment may be implicated in the development and progression of DR in patients with type 2 diabetes." (PMID 34283877, 2021). "Therefore, insulin therapy may associate with decreased risk of macrovascular complications such as atherosclerosis and death in patients with type 2 diabetes, especially in those with high cardiovascular risk." (PMID 33598483, 2021). "Pancreatic β-cell loss and failure with subsequent deficiency of insulin production is the hallmark of type 1 diabetes (T1D) and late-stage type 2 diabetes (T2D)." (PMID 34940547, 2021). "However, glycogen synthesis is compromised in insulin-resistant or type 2 diabetes patients, which could be caused by GS dysfunction or by a lack of glucose to be stored as glycogen, which, in turn, reduces GS activity." (PMID 33573178, 2021). "Finally, compound 11 exerteda benefic effect on mice blood glucose level by increasing plasmainsulin concentrations, thus confirming its potential applicationfor treating type-2 diabetes and any other conditions associated witha low level of insulin secretion/production." (PMID 34213320, 2021). "Islet dysfunction and destruction lead to the hypofunction of insulin secretion, which is the common cause for both type 1 and type 2 diabetes mellitus (T2DM)." (PMID 34642299, 2021). "The pathophysiology of type 2 diabetes mellitus (T2D) involves increased peripheral insulin resistance and a loss of pancreatic β-cell function (resulting in reduced insulin secretion) as the main contributors to a gradually deteriorating glycemic control." (PMID 34371883, 2021). "Type 2 Diabetes Mellitus (T2DM) is a group of metabolic syndrome characterized by hyperglycemia associated with the defect of insulin action." (PMID 33858419, 2021). "Type 2 diabetes mellitus (T2DM) is the result of insulin resistance and is caused by the failure of the body’s cells to use insulin properly, at times combined with an absolute insulin deficiency." (PMID 35010422, 2021). "Type 1 diabetes (T1D) presents an absolute insulin deficiency resulting from the autoimmune impairment of insulin-generating β cells, while type 2 diabetes (T2D) displays a relative insulin deficiency due to metabolic dysfunction." (PMID 34603195, 2021). "Type 2 diabetes mellitus (T2DM) is a complex endocrine disease caused by a combination of environmental and genetic factors, leading to islet failure or insufficient insulin action." (PMID 34938667, 2021). "If the resulting β cell-like cells are capable of glucose-regulated insulin secretion, they might be able to compensate in pancreatic cancer patients the insulin deficiency resulting from radical surgery or a long-term history of type II diabetes." (PMID 34572891, 2021). "Type 2 diabetes mellitus (T2DM) is a metabolic disease characterized by chronic hyperglycemia caused by defects in insulin secretion, which can contribute to the development of resistance to its action." (PMID 33613481, 2021).
type 2 diabetes (continued). "Surprisingly, we found that, similar to the recommended hypoglycemic drug of insulin, the use of metformin or sulfonylureas was also the independently protective factor for the long-term all-cause death in patients with pulmonary TB and type 2 diabetes comorbidity." (PMID 34513785, 2021). "Importantly, our study also suggests the benefits of postnatal L-leucine supplement to improve glucose tolerance in SE offspring by improving their blood insulin levels, which may potentially reduce the risk of type 2 diabetes." (PMID 34276421, 2021). "In addition, our findings could also have implications for pathology associated with Type 2 diabetes as in our previous work, we also have demonstrated that α-catenin inhibits insulin secretion in pancreatic β-cells." (PMID 34139004, 2021). "An imaging method for detecting β-cell function in real-time in the rodent pancreas could provide new insights into the biological mechanisms involving loss of β-cell function during development of type 2 diabetes and for testing of new drugs designed to modulate insulin secretion." (PMID 35173681, 2021). "Interestingly, pharmacological lowering of hepatic triglyceride content in type 2 diabetes by rosiglitazone, a PPARγ receptor agonist, is also associated with a significant increase in insulin clearance within 16 weeks, and this effect is present without significant weight loss." (PMID 34360563, 2021). "Therefore, we hypothesized that insulin secretion in type 2 diabetes is associated with TYK2PV, which might reveal a unique and novel disease type of type 2 diabetes." (PMID 33799705, 2021). "In stable patients with type 2 diabetes (T2D), insulin treatment is associated with elevated risk for major adverse cardiovascular events (MACE)." (PMID 34158057, 2021). "After adjustment for age, DD, hypertension, smoking status, and alcohol use (Model I), insulin therapy was independently associated with the presence of carotid plaque in both women (OR: 1.619, 95% CI: 1.200–2.185, p = 0.002) and men (OR: 1.461, 95% CI: 1.103–1.935, p = 0.008) with type 2 diabetes." (PMID 33598483, 2021). "Hence ethnic differences in insulin sensitivity and type 2 diabetes risk may be linked to the variation in the upregulated oxidative stress." (PMID 34299261, 2021). "Finally, our work supports the hypothesis that pre- and postnatal maldevelopment of islets, leading to insufficient insulin secretion, may be an important, yet underappreciated, risk for the subsequent manifestation of type 2 diabetes." (PMID 33525575, 2021). "This may be considered a type of dysfunction as increased basal insulin secretion values are associated with a worse clinical and metabolic phenotype in adults and adolescents and predicts deterioration of glucose control over time and thus type 2 diabetes." (PMID 32042314, 2020). "Interestingly, type 2 diabetes and obesity are associated with increased pancreatic duct cell replication and not until recently it has been shown that in states of increased insulin demand, ductal cells contribute to the compensatory β cell pool by differentiation and/or neogenesis [37••]." (PMID 32239341, 2020). "Traditionally, intensive insulin-based regimens have been hampered by concomitant increase of hypoglycemia, and intensification of glucose-control with insulin use has even been linked to an increase of all-cause mortality in vulnerable individuals with type 2 diabetes." (PMID 33195459, 2020). "Notably, single-nucleotide polymorphisms in and near the ADRA2A gene (encoding α2A-adrenergic receptor) have been correlated with increased fasting glycemia and type 2 diabetes risk; impaired glucose-stimulated insulin secretion is a factor in this increased risk." (PMID 33178692, 2020).
type 2 diabetes (continued). "Taken together, these findings indicate the involvement of CB in the counterregulatory responses to hypoglycemia, which is especially important in cases of diabetic patients under insulin treatment, and suggests that CB malfunctions could be associated with the development of type 2 diabetes." (PMID 32698380, 2020). "The unfalsifiability of the insulin resistance hypothesis arising out of this circularity has halted any attempts towards realistic assessments of the true causes of fasting hyperglycaemia in type 2 diabetes." (PMID 33365205, 2020). "The in-depth analyses reported on oxidative stress being the perpetrator to enhance beta-cell dysfunction as a final result, together with the potential activation of pathways linked to beta-cell apoptosis that may be the resulting cause of an insulin gene expression deficit in type 2 diabetes." (PMID 32270277, 2020). "We use this distinction below to re-examine the role of insulin in glucose homeostasis and show that the failure to distinguish between driver and navigator causality has led to a fundamentally flawed understanding of glucose homeostasis and type 2 diabetes in particular." (PMID 33365205, 2020). "However, the strongest association with hypoglycemia-related ED visits and hospitalization was the choice of glucose level–lowering medication (for patients with type 2 diabetes), with use of prandial insulin and, to a lesser degree, basal insulin or sulfonylurea, conferring the highest risk." (PMID 31922562, 2020). "Type 2 diabetes mellitus (T2DM) is associated with a number of disturbances of immune status and metabolic pathways that can be detected not only in insulin sensitive tissue but also in easily accessible peripheral blood mononuclear cells (PBMC)." (PMID 33658980, 2020). "In Type 1 diabetes (T1DM), insulin secretion is potentially impaired owing to a vitamin D deficiency and is improved through dietary vitamin D repletion, while a lower vitamin D intake or lower 25(OH)D levels might increase the Type 2 diabetes risk." (PMID 32538430, 2020). "Importantly, α-cells of T2D are resistant to inhibition by insulin and somatostatin, which might underlie the hyperglucagonemia in type-2 diabetes." (PMID 32312960, 2020). "Vitamin D deficiency is a risk factor that predisposes patients to type 2 diabetes mellitus (T2DM) since it impairs the production and secretion of insulin." (PMID 33680012, 2020). "The potential mechanisms of association could be that consumption of fruit and vegetables helps to regulate weight and adiposity, as well as glucose-insulin homoeostasis and the inflammatory status of the participants, thus leading to a reduced risk of type 2 diabetes." (PMID 32641421, 2020). "Type 2 diabetes mellitus (T2DM) is a chronic metabolic disorder characterized by hyperglycemia, loss of insulin sensitivity and progressive dysfunction of pancreatic β cells." (PMID 32470060, 2020). "Type 2 diabetes mellitus (T2DM) is a metabolic disease caused by genetic or environmental factors, or both, including insufficient or relative deficiency of insulin and dysfunction of pancreatic islets, leading to chronic hyperglycemia." (PMID 32796637, 2020). "Dysfunction of insulin signaling is a condition associated with multiple pathological states of chronic diseases, such as obesity, type 2 diabetes mellitus (T2DM) and metabolic syndrome." (PMID 33291072, 2020). "Moreover, type 2 diabetes is speculated to develop as these influences block the body's insulin signals to cause insulin resistance." (PMID 33133214, 2020). "Thus, investigating the effects of combined aerobic and resistance exercise training on insulin sensitivity in individuals predisposed to developing type 2 diabetes provides an opportunity to examine potential therapies and reduce the overall prevalence of type 2 diabetes." (PMID 32231642, 2020).